RNU6-143P (RNA, U6 small nuclear 143, pseudogene)
Gene: Small nuclear RNA gene on chromosome 3 (124,407,691 to 124,407,783, forward strand). Ensembl gene ENSG00000252751.
Homologues: Orthologues: chimpanzee U6 (100% identical), dog U6 (84% identical), dog U6 (77% identical), guinea pig U6 (76% identical), rat LOC120099047 (74% identical). Paralogues in human: RNU6-15P (88% identical), RNU6-672P (88% identical), RNU6-1060P (87% identical), RNU6-116P (87% identical), RNU6-125P (87% identical), RNU6-30P (87% identical), RNU6-33P (87% identical), RNU6-558P (87% identical), RNU6-901P (87% identical), RNU6-1 (86% identical), RNU6-12P (86% identical), RNU6-132P (86% identical), and 1287 more.